LINC01234 (long independently transcribed non-coding RNA 1234)
Synonyms: onco-lncRNA-32; MBOP; LCAL84
Gene: Long non-coding RNA gene on chromosome 12 (113,583,886 to 113,773,726, reverse strand). Ensembl gene ENSG00000249550.
Diseases named in the same sentence as LINC01234 in open-access papers:
LINC01234 is named in the same sentence as 34 diseases in open-access papers, as found by Europe PMC text mining. Sharing a sentence is not in itself a finding about the gene and the disease. The quoted sentences say what the papers report.
gastric cancer (20 papers, 2014 to 2024). A primary or metastatic malignant neoplasm involving the stomach. "In our previous study, we identified a gastric cancer-associated lncRNA LINC01234, which promoted gastric tumorigenesis via sponging miR-204-5p to regulate CBFB expression." (PMID 31959200, 2020). "Besides, LINC01234 expression was significantly upregulated in gastric cancer tissues and was associated with larger tumor size, advanced TNM stage, lymph node metastasis, and shorter survival time." (PMID 33088626, 2020). "LINC01234 is upregulated in colorectal cancer, gastric cancer, and oral cancer and high expression correlates with poor prognosis." (PMID 35303965, 2022). "For example, in gastric cancer, LINC01234 functions as an miR-204-5p sponge to up-regulate the expression of CBFB." (PMID 35765893, 2022). "For example, LINC01234 acts as a ceRNA to regulate CBFB expression by sponging miR-204-5p to promote gastric cancer cell proliferation." (PMID 33658048, 2021). "The proliferation and tumor formation abilities of gastric cancer cells are inhibited by knockdown of LINC01234, a potential molecular target of tumor therapy." (PMID 32962742, 2020). "In addition, the lncRNA LINC01234 promotes the growth of gastric cancer by acting as a ceRNA for miR-204-5p." (PMID 34749766, 2021). "LINC01234 acts as a ceRNA to modulate CBFB expression in gastric cancer by absorbing miR-204-5p." (PMID 32110804, 2020). "For instance, Long noncoding RNA LINC01234 was identified to function as a competing endogenous RNA and sponging miR-204-5p; the CBFB expression was regulated by gain or loss of expression of LINC01234, thus, affecting the gastric cancer tumorigenesis." (PMID 31729423, 2019). "Our previous and other studies have revealed the involvement of upregulated LINC01234 in regulating gastric cancer and colon cancer cells proliferation, and we aimed to investigate whether LINC01234 overexpression also contribute to cancer cells metastasis in this study." (PMID 31959200, 2020). "First, the mRNA expression of LINC01234 in paired tissue samples from patients with CRC, lung cancer, kidney cancer, liver cancer, and gastric cancer was detected." (PMID 35565466, 2022). "Recently, partial functions and mechanisms of LINC01234 (also known as LCAL84) were reported in cancers, such as gastric cancer, esophageal cancer, and colorectal adenocarcinoma." (PMID 33088626, 2020). "Moreover, LINC01234 promotes cells proliferation in vitro and tumor growth in vivo by acting as a competing endogenous RNA (ceRNA) for miR-204-5p and regulating core-binding factor β (CBFB) expression in gastric cancer (GC)." (PMID 34327141, 2021). "Secondly, although LINC01234 functioned as ceRNA to regulate CBFB expression by sponging miR-204-5p in gastric cancer, we did not identify any miRNAs as direct targets of LINC01234 to investigate whether LINC01234 was a ceRNA for miRNAs in ccRCC." (PMID 33088626, 2020). "Moreover, LINC01234 could serve as ceRNA to regulate core-binding factor β (CBFB) expression by sponging miR-204-5p to regulate the apoptosis, growth arrest and tumorigenesis in gastric cancer." (PMID 33088626, 2020).
colon cancer (11 papers, 2014 to 2022). "LINC01234 has emerged as an important regulator that is upregulated in colon cancer and is associated with poor prognosis, and its knockdown significantly inhibitted tumorigenesis in hepatocellular carcinoma." (PMID 36408190, 2022). "The survival analysis showed that a high expression of AC008760.1, AC009237.14, AC083809.1, AL391422.4, AL445645.1, LINC01063, LINC01234, and LINC02381 was associated with a poor prognosis in colon cancer." (PMID 32425969, 2020). "Interestingly, also in colon cancer, the long non-coding RNA LINC01234 and the circular RNA-103809 have been shown to act as competing endogenous RNAs (ceRNA) or ‘sponges’ of miR-642a-5p, thereby reducing its bioavailability and tumor suppressive functions." (PMID 34504167, 2021). "Furthermore, LINC01234 enhances colon cancer cell proliferation via the upregulation of serine hydroxymethyltransferase 2 (SHMT2) by competitively binding with miR-642a-59." (PMID 33246471, 2020). "Similarly, LINC01234 was reported to be highly expressed in colon cancer tissues, and colon cancer patients with upregulated LINC01234 have a shorter survival time." (PMID 33246471, 2020). "The GEPIA database showed that AC008760.1, AC009237.14, AC083809.1, AL391422.4, AL445645.1, LINC01063, and LINC01234 were highly expressed in colon cancer and that AC016027.1 has low expression in colon cancer." (PMID 32425969, 2020). "Similarly, LINC01234 acted as a ceRNA of miR-642a-5p, resulting in the suppression of the endogenous serine hydroxymethyl transferase 2 (SHMT2), suggesting that the LINC01234-miR642a-5p-SHMT2 axis plays a key role in colon cancer." (PMID 31941509, 2020). "In addition, the expression of AC008760.1, AC009237.14, AL391422.4, and LINC01234 was significantly correlated with tumor cell metastasis, and the expression of AC008760.1, AL445645.1, AC009237.14, and AL391422.4 was significantly related to the clinical stage of colon cancer." (PMID 32425969, 2020).
breast carcinoma (6 papers, 2014 to 2025). "LINC01234 has been shown to be significantly associated with cancer treatment and prognosis in colon, gastric, and breast cancer." (PMID 31850229, 2019). "The LINC01234 gene is a long non-coding RNA (lncRNA) signature which is pervasive in different stages, subtypes and age groups of breast cancer." (PMID 31856825, 2019). "The LINC01234 gene shows a higher expression level in group 1 of breast cancer samples than in group 2 of breast cancer samples or normal samples." (PMID 31856825, 2019). "LINC01234 is negatively related to miR-190b, and miR-190b is down-regulated in breast cancer, thus the expression level of LINC01234 can be higher in breast cancer." (PMID 31856825, 2019). "In this study, LINC01234 was found to be negatively related to miR-190b, which was similar to LINC01234 in sequences, and miR-190b was reported to be down-regulated in breast cancer and was related to estrogen receptor in several studies." (PMID 27338266, 2016).
non-small cell lung carcinoma (5 papers, 2020 to 2023). A group of at least three distinct histological types of lung cancer, including non-small cell squamous cell carcinoma, adenocarcinoma, and large cell carcinoma. "LncRNA LINC01234-induced by SP1 as a ceRNA promotes non-small cell lung cancer by modulating OTUB1." (PMID 31737900, 2020). "LINC01234 interacts with HNRNPA2B1, leading to the recruitment of DGCR8 and promoting the processing and maturation of miR-106b-5p, which inhibits CRY2 and promotes the growth of non-small cell lung cancer (NSCLC) cells." (PMID 37178254, 2023).
hepatocellular carcinoma (4 papers, 2022 to 2025). A malignant tumor that arises from hepatocytes. "In hepatocellular carcinoma (HCC), LINC01234 was involved in proliferation and chemoresistance through the MAGEA3/LINC01234/miR-31-5p axis." (PMID 35765893, 2022).
liver cancer (4 papers, 2020 to 2022). An epithelial or non-epithelial malignant neoplasm that arises from the liver. "Suppression of LINC01234 expression was found to restrain liver cancer progression via the mediation of the miR-513a-5p/USP4/TGF-β axis." (PMID 35923244, 2022). "Previous studies have shown an upregulation of LINC01234 in ovarian cancer, liver cancer, and triple-negative breast cancer (TNBC)." (PMID 35923244, 2022). "Taken together, LINC01234 silencing significantly decreased the proliferation of liver cancer cells." (PMID 33178601, 2020). "Altogether, LINC01234 knockdown inhibited the tumorigenesis of liver cancer via mediation of miR-513a-5p/USP4 axis." (PMID 33178601, 2020). "Altogether, knockdown of LINC01234 notably attenuated the tumor growth of liver cancer through inactivation of TGF-β signaling in vivo." (PMID 33178601, 2020). "Our research found miR-513a-5p antagomir partially reversed the inhibitory effect of LINC01234 knockdown on liver cancer, further verified the function of miR-513a-5p in liver cancer progression." (PMID 33178601, 2020). "For the purpose of exploring the mechanism by which LINC01234 mediated the progression of liver cancer, Starbase1 was performed." (PMID 33178601, 2020). "In summary, silencing of LINC01234 notably inhibited the tumorigenesis of liver cancer via mediation of miR-513a-5p/USP4/TGF-β1 axis." (PMID 33178601, 2020). "Current study suggested that LINC01234 likely promote tumorigenesis of liver cancer, particularly during the advanced stages of the disease; LINC01234 might serve as an important biomarker for diagnosis and treatment of liver cancer." (PMID 33178601, 2020). "The expression of LINC01234 in liver cancer cells was much higher than that in normal liver cells." (PMID 33178601, 2020). "The present findings indicate that LINC01234 knockdown could suppress liver cancer cell proliferation via inducing apoptosis." (PMID 33178601, 2020). "Moreover, knockdown of LINC01234 significantly suppressed the proliferation and invasion of liver cancer cells via inducing the apoptosis." (PMID 33178601, 2020). "In addition, knockdown of LINC01234 greatly inhibited the migration and invasion of liver cancer cells." (PMID 33178601, 2020). "Moreover, our findings suggested that knockdown of LINC01234 inactivated EMT process in liver cancer cells." (PMID 33178601, 2020). "Consistent to these findings, we suggested that LINC01234 could promote liver cancer through activation of TGF-β1/EMT signaling." (PMID 33178601, 2020). "In addition, LINC01234 knockdown inhibited the tumorigenesis of liver cancer via inactivating TGF-β signaling." (PMID 33178601, 2020). "Moreover, LINC01234 shRNA1 and shRNA2 were stably transfected into liver cancer cells, and the expression of LINC01234 in liver cancers was significantly downregulated when transfected with LINC01234 shRNA." (PMID 33178601, 2020). "Downregulation of LINC01234 could inhibit the tumorigenesis of liver cancer via mediation of miR-513a-5p/USP4/TGF-β axis." (PMID 33178601, 2020). "In addition, LINC01234 knockdown could inhibit the growth, migration and invasion of liver cancer cells via mediating the miR-513a-5p/USP4 axis." (PMID 33178601, 2020). "Furthermore, silencing of LINC01234 notably inhibited the tumor growth of liver cancer in vivo." (PMID 33178601, 2020). "Thus, LINC01234 may act as a key biomarker for diagnosis and treatment of liver cancer." (PMID 33178601, 2020). "Thus, LINC01234 might serve as a new target for the treatment of liver cancer." (PMID 33178601, 2020). "In contrast, knockdown of LINC01234 greatly decreased the expression of vimentin and α-SMA in liver cancer cells." (PMID 33178601, 2020).
clear cell renal cell carcinoma (3 papers, 2020 to 2022). "LINC01234 was also shown to regulate the progression of clear cell renal cell carcinoma cells by HIF-2a pathways." (PMID 35923244, 2022).
esophageal cancer (3 papers, 2020 to 2022). A primary or metastatic malignant neoplasm involving the esophagus. "LINC01234 was significantly associated with the prognosis of colorectal adenocarcinoma and the malignant biological behaviors of esophageal carcinoma cells including proliferation, migration, invasion and apoptosis." (PMID 33088626, 2020). "LINC01234 was upregulated and had oncogenic potentials in esophageal carcinoma cells in vitro." (PMID 33088626, 2020). "However, a previous report indicated that LINC01234 silencing could exert an anti-oncogenic effect in esophageal cancer cells through sponging miR-193a-5p." (PMID 33178601, 2020).
esophageal squamous cell carcinoma (3 papers, 2014 to 2020). Esophageal squamous cell carcinoma (ESCC) is a type of esophageal carcinoma (EC) that can affect any part of the esophagus, but is usually located in the upper or middle third. "The previous study found LINC01234 is highly expressed in esophageal squamous cell carcinoma (ESCC)." (PMID 32011780, 2020). "LINC01234 is up-regulated in esophageal squamous cell carcinoma (ESCC) and the three-lncRNA signature including LINC01234 could accurately predict survival of patients with ESCC." (PMID 28484081, 2017).
lung carcinoma (3 papers, 2020 to 2023). "HNRNPA2B1 could interact with LINC01234 to promote lung cancer progression." (PMID 33134163, 2020).
lymph node metastasis (3 papers, 2019 to 2020). "In view of the strong association of Linc01234 expression with lymph node metastasis (N stage), the effect of Linc01234 on cell migration and invasion in OSCC cells was further explored." (PMID 32041570, 2020). "High Linc01234 expression was positively related to advanced T stage, lymph node metastasis and poor pathological differentiation." (PMID 32041570, 2020). "Higher LINC01234 expression level was also significantly correlated with tumor size (Chi-square test, P = 0.042), TNM stage (Chi-square test, P = 0.015), and lymph node metastasis (Chi-square test, P = 0.011) in NSCLC patients, but not with other factors, including sex and age." (PMID 31959200, 2020).
triple-negative breast carcinoma (2 papers, 2022 to 2025). An invasive breast carcinoma which is negative for expression of estrogen receptor (ER), progesterone receptor (PR), and human epidermal growth factor receptor 2 (HER2). "LINC01234 was also shown to promote cell proliferation and tumor metastasis in triple-negative breast cancer (TNBC)." (PMID 35923244, 2022). "In triple-negative breast cancer, mechanistic investigations demonstrated that LINC01234 might act as a competing endogenous RNA for miR-429 to upregulate SYNJ1 expression to induce cell proliferation and migration and impair cell apoptosis." (PMID 39991576, 2025).
head and neck cancer (1 paper, 2020). A primary or metastatic malignant neoplasm affecting the head and neck. "RT-qPCR results shown that Linc01234 silencing increased the expression levels of miR-433-3p, which was dramatically downregulated in head and neck cancer tissues." (PMID 32041570, 2020). "In addition, the starBase database analysis shown that high expression of Linc01234 in head and neck cancer patients was closely correlated with short overall survival (OS)." (PMID 32041570, 2020).
lung adenocarcinoma (1 paper, 2020). A carcinoma that arises from the lung and is characterized by the presence of malignant glandular epithelial cells. "We first analyzed lung adenocarcinoma and lung squamous cell carcinoma RNA sequencing datasets from TCGA and found LINC01234 was upregulated in NSCLC tissues compared with adjacent tissues." (PMID 31959200, 2020). "In addition, we found a significant correlation between LINC01234 expression and lung adenocarcinoma stage from TCGA dataset." (PMID 31959200, 2020).
melanoma (1 paper, 2021). A malignant, usually aggressive tumor composed of atypical, neoplastic melanocytes. "Our analysis of two SFPQ-enriched lncRNAs, LINC00511 and LINC01234, both with established roles as oncogenes in other cancer backgrounds, revealed that knockdown of these genes impaired melanoma viable cell growth, migration and, in the case of LINC00511, cellular respiration." (PMID 34218270, 2021). "Functional analysis of two SFPQ-enriched lncRNA, LINC00511 and LINC01234, demonstrated that these genes independently contribute to the melanoma phenotype and a more detailed analysis of LINC00511 indicated that this occurs in part via modulation of the miR-625-5p/PKM2 axis." (PMID 34218270, 2021). "In contrast, A2058-specific SFPQ-enriched lncRNA included LINC00511, DUXAP8, TMEM51-AS1, FOXD2-AS1 and LINC01234, all of which have been shown to drive metastasis in a range of cancers via various mechanisms, however, only FOXD2-AS1 has been associated previously with melanoma." (PMID 34218270, 2021).
oral squamous cell carcinoma (1 paper, 2020). "However, the potential biological functions and clinical importance of Linc01234 in oral squamous cell carcinoma (OSCC) remain unclear." (PMID 32041570, 2020).
tumor (18 papers, 2019 to 2022). "The high-risk subgroup significantly overexpressed LINC01234, which is known to be a key marker for tumor proliferation and metastasis." (PMID 36408190, 2022). "We screened out LINC01234, found to be significantly increased in BC tissues, associated with a poor prognosis, and positively correlated with tumor size of BC." (PMID 35923244, 2022). "Several studies have shown that LINC01234 is closely associated with tumor cell proliferation and metastasis." (PMID 36408190, 2022). "We found that LINC01234 had tumor-promoting effects in BC by attenuating the suppression of miR-525-5p on CSDE1." (PMID 35923244, 2022). "The lncRNA NKX2-1-AS1 promotes tumor progression and angiogenesis by sponging miR-145-5p in GC, while LINC01234 promotes GC cell proliferation and inhibits cell apoptosis by sponging miR-204-5p." (PMID 35017465, 2022). "Knockdown of this protein, which is regulated by LINC01234 and miR-31-5p, affects tumor proliferation, invasion and cisplatin-induced apoptosis." (PMID 36367777, 2022). "The expressions of p-Smad2 and p-Smad3 in tumor tissues were notably decreased by LINC01234 knockdown." (PMID 33178601, 2020). "In the present study, we investigated the molecular mechanisms through which LINC01234 regulated the tumor progression-related behavior of NSCLC cells, and found that LINC01234 interacted with several RNA-binding proteins, including Ago2, EZH2, LSD1 and SUZ12." (PMID 31959200, 2020). "We found that LINC01234 expression level was positively correlated with the tumor size of BC." (PMID 35923244, 2022). "Moreover, the GSE33371 dataset shows that a higher LINC01234 expression implied larger tumor volume when the average value of LINC01234 expression was taken as the cutoff." (PMID 35765893, 2022). "One of 2 TFs, ELK1, is an important regulator and known to activate many lncRNAs including TRPM2‐AS, MIR100HG, and HOXA10‐AS in cancer until now, indicating ELK1 may induce expression of LINC01234 to promote tumor progression in GC too." (PMID 32011780, 2020). "We found that Linc01234 expression was closely correlated with T stage, N stage and pathological stage (P < 0.05), however there was no statistical significance between Linc01234 and age, gender, tumor site or distant metastasis." (PMID 32041570, 2020). "Indeed, complementary in vivo studies using a mouse model revealed that LINC01234 plays a key role in tumor metastasis." (PMID 31959200, 2020). "Consistently, knockdown of LINC01234 notably downregulated the tumor weights of mice." (PMID 33178601, 2020). "Tumor sizes of mice were significantly decreased by LINC01234 knockdown." (PMID 33178601, 2020). "Hence, we hypothesized that LINC01234 plays a pro-tumor role in tumor progression." (PMID 35765893, 2022). "Targeting the LINC01234/miR-124-3p/GRB2 axis reportedly increased the expression of miR-124-3p and inhibited the expression of the GRB2 protein through the downregulation of LINC01234, which ultimately decreased the proliferation of the MM tumor cells." (PMID 36466549, 2022).